FLNA (filamin A)
Diseases named in the same sentence as FLNA in open-access papers (continued):
Sharing a sentence is not in itself a finding about the gene and the disease.
cancer (continued). "In some cases, different stages of cancers have varied level of filamin-A expression." (PMID 23388158, 2013). "FLNA may mediate the effects of signaling pathways on both cancer and endothelial cell motility during tumorigenesis." (PMID 22857000, 2012). "Hence, it could be considered as a potential lead molecule for inhibiting protein Filamin A in the treatment of cancer." (PMID 37720273, 2023). "However, FOXA1 also enhances a small subset of NMD-determinant exons, such as FLNA exon 30, which predicts disease recurrence, and therefore may drive a more aggressive cancer phenotype." (PMID 36170835, 2022). "Indeed, whether in the cytoplasm or the nucleus, FLNA facilitates the interaction of signaling molecules or transcription factors to either promote or prevent cancer." (PMID 37435454, 2022). "Previous studies demonstrated that FLNA was involved in the control of cell mobility and extracellular matrix degradation in some tumoral tissues and FLNA knockdown enhanced metalloproteinase activity, which stimulated invasion, cancer cell migration and metastasis formation." (PMID 30718563, 2019). "FLNA may be significant in migration, invasion and metastasis of other cancers also." (PMID 26134617, 2015). "In addition, variable expression levels of filamin-A protein among different cancers may serve as a useful tool for individualized therapy and outcome prediction." (PMID 23388158, 2013). "CNa 29 significantly reduced filamin A cleavage, vimentin expression, TWIST1 transcription, and the expressions of genes related to cancer stemness and increased the efficacy of doxorubicin, a chemotherapy drug commonly used for TNBC in clinical settings." (PMID 40151834, 2025). "In conclusion, we demonstrated that FLNA regulates Wee1 expression by promoting its degradation, suggesting that low FLNA typical of ACC leads to increased Wee1 with consequent cancer cells growth." (PMID 39528354, 2025). "The PI3K-Akt signaling and proteoglycans in cancer were significantly enriched, involving proteins such as COL1A1, FN1, THBS1, FLNA, and ACTB." (PMID 40710368, 2025). "Treatment of these cancer cells with leupeptin, a protease inhibitor, and/or ALLM, a calpain specific inhibitor, blocks extracellular Ca++-mediated cleavage of FLNA and thereby reduces cellular migration in androgen receptor deficiency." (PMID 39195282, 2024). "The SNV landscape map revealed that the SNV of FLNA, FLNB, and MYH9 was frequently detected in various cancers." (PMID 38584831, 2024). "Most signaling pathways in pan-cancer, including ACTB, FLNA, MYH9, MYH10, and TLN1, exhibited high activation levels in the epithelial-mesenchymal transition (EMT) pathway, but consistent inhibition of the cell cycle, DNA damage response, and hormone AR." (PMID 38862242, 2024). "DSTN and FLNB were downregulated when ACTIN4, INF2, MHY10, FLNA, PDLIM1, and IQGAP1 were upregulated in THCA cancer tissues." (PMID 38584831, 2024). "We identified distinct genes including KLK4, FN1, PBOV1, TPM2, and FLNA which are known to be involved in PCa pathways along with IGF1, TPD52, and SRSF1 that are involved in different cancer pathways." (PMID 37218885, 2023). "Equally, altered protein levels of FLNA, HSPA7, HGF, ERO1A, and GARS1, have been related to cancer migration, adhesion, poor patient prognosis, and metastasis." (PMID 35008958, 2022). "Multiple studies report a role for FLNA and FLNB in cancer cell migration, but the role of FLNC remains largely unexplored." (PMID 33934493, 2021). "Five—Using STRING database, we found that it had interactions with several proteins involved in different cancers such as TXNDC9, GXYLT2, POFUT1, XXYLT1, FLNA, and ZC3H12C." (PMID 35140741, 2021). "Numerous studies show the activation of FLNA is directly related with oncogenesis and metastasis in different cancers, we assumed that AZGP1 promoted cancer development and metastasis mediated by FLNA." (PMID 31632499, 2019).
cancer (continued). "Putative coregulators of MKL1 activity were investigated by Western blotting for suppressor of cancer cell invasion (SCAI) and filamin A (FLNA)." (PMID 29065889, 2017). "Several studies have described that FLNA and FLNB interact with a number of proteins to regulate signaling events involved in cell shape and migration in cancer." (PMID 28031525, 2017). "Numerous studies have reported that expression of FLNA and FLNB promote cancer invasion and metastasis." (PMID 28031525, 2017). "The log fold changes and, thus, the rankings among all the DEGs are almost the same for each of the found key genes ITGA2B, FLNA, GRB2, FCGR2A, and APP across all three datasets, confirming that these are consistently differentially expressed in NSCLC vs. healthy/non-cancer." (PMID 41226816, 2025). "MDA‐MB‐231 cells were treated with CNa 29 to determine whether pharmacological inhibition of calpain 2 by CNa 29 prevents filamin A cleavage‐induced HIF1α nuclear translocation, TWIST1 expression, EMT, cancer stemness, and metastasis." (PMID 40151834, 2025). "MHY9, INF2, FLNA, MYH10, FLNB, FLN1, and ACTB were upregulated in HNSC cancer tissues." (PMID 38584831, 2024). "Moreover, targeted bisulfite NGS methodology validated microarray data on four selected genes (GNL3L, FHL1, FLNA, and PGRMC1), confirming that they were hypomethylated in patients with cancer anorexia in comparison with controls." (PMID 39519555, 2024). "Phosphorylation of FLNA at S2152 was shown to occur by mTOR and by IGF-1 in cancer cells." (PMID 37457922, 2023). "The roles of FLNA and MYH9 in tumorigenesis and development have been reported in cancer." (PMID 34093822, 2021). "Filamin A (FLNA), plastin-2 (LCP1), coronin-1A (CORO1A), and formin-like-1 (FMNL1) also affect cytoskeletal dynamics by modulating actin filaments which eventually prompt cancer mobility and invasion." (PMID 32326232, 2020). "While the role of HSP90β in cancer progression is well documented in the literature, the specific roles of filamin A and EPRS in cancer are not well studied." (PMID 29596499, 2018). "The fact that filamin A acts in DNA damage repair suggests that the lack of filamin A confers cancer cells more sensitive to DNA damage treatment and allows better prognosis." (PMID 24858105, 2014). "In addition, enhanced expression of filamin A (FLNA) may relate to cytoskeleton actin and tubulin reorganization as seen in different cancer models undergoing EMT." (PMID 36463238, 2022). "Correspondingly, compared to noncancerous MCF-12A epithelial cells, MDA-MB-231 cancer cells exhibited an increase in filamin A and EPRS protein carbonylation, decreased total SOD activity, and increased autophagy, but not increased HSP90β protein carbonylation." (PMID 29596499, 2018). "The upregulation of gene products associated with migration and invasion (osteopontin, MMP1, vimentin, filamin-A, and β-actin) and gene products for extracellular matrix molecules and their modulators (fibronectin, collagen, ITGBL1, and MXRA5) reflects the invasive nature of this cancer." (PMID 25861239, 2015). "The apparent discrepancies among the literature strongly indicate that levels of filamin-A in the cancer cells may not be the sole indicator of predicting whether a cancer is more or less metastatic." (PMID 23388158, 2013). "Similarly, “cancer-specific” escapees generally exhibited higher enrichment at their TSS in the cell lines where they escaped compared to HMECs with a few exceptions (e.g., CFP, FLNA, and MOSPD1 in MDA-MB-436 cells displayed no obvious differences in TSS profiles)." (PMID 25653311, 2015).
infection (17 papers, 2011 to 2026). The state of being infected such as from the introduction of a foreign agent such as serum, vaccine, antigenic substance or organism. "Filamin A (FLNa), a cytoskeletal protein, is involved in cytoskeleton remodeling to construct a barrier to infection and participates in virus entry and release." (PMID 41615268, 2026). "To characterize the key steps by which Filamin A expression and phosphorylation are required for KSHV primary infection, we further investigated the ability of viral entry into cells and nuclei after primary infection in Filamin A WT, KO and KI cells." (PMID 41284726, 2025). "Further, KSHV de novo infection using purified Bac16 or STOP45 virion particles was quantitated in Filamin A WT, S2152A KI or KO HEK293-mCherry cells." (PMID 41284726, 2025). "Taken together, our results demonstrated that the ORF45-Filamin A phosphorylation axis promotes cell detachment and migration and facilitates viral de novo infection and cell-to-cell transmission during KSHV lytic cycles." (PMID 41284726, 2025). "The increased level of Filamin A phosphorylation during primary infection with Bac16 viruses was also abolished when cells were treated with the RSK inhibitor BI-D1870 or SL0101." (PMID 41284726, 2025). "As a result, compared with those in WT cells, the levels of viral gene expression (both the lytic gene RTA and the latent gene LANA) at 24 h post infection were decreased in Filamin A KO and KI cells." (PMID 41284726, 2025). "Filamin-A is another actin-adaptor protein relevant to how HIV-1 modulates the cortical actin cytoskeleton to assure productive infection." (PMID 37685911, 2023). "We found HEV invasion activated the expression of FLNA at early stage of infection, then inhibited its expression after entrance at 24 hpi." (PMID 37264422, 2023). "An increase in productive infection was detected after knockdown of FLNA, HMGB3, PTBP1, HSP90AA1, and KIF2C (green bars)." (PMID 34194479, 2021). "As infection progressed, at 12 h.p.i, FLNA was found to co-localize with NP majorly at the peri-nuclear region, potentially suggesting the involvement of FLNA in the transport of NP from the nucleus to the cytoplasm." (PMID 33101257, 2020). "One protein that was perturbed by infection (filamin A) was used to further elucidate the mechanism of U. parvum-induced disruption in human benign prostate cells (BPH-1)." (PMID 21507248, 2011). "Specifically, the concentration of profilin 1, α actinin, vinculin, and filamin A were found to be significantly altered by infection." (PMID 21507248, 2011). "In vitro infection studies with BPH-1 cells confirmed that U. parvum colonization interfered with the normal distribution of intracellular filamin A by inducing phosphorylation of the protein at serine2152." (PMID 21507248, 2011). "We evaluated the impact of U. parvum infection on filamin A using the benign prostate hyperplastic (BPH-1) cell line as a model of infection." (PMID 21507248, 2011). "Notably, HEV interacted with FLNa at the early stage of infection and remarkably inhibited the expression of FLNa in vivo and in vitro." (PMID 41615268, 2026). "Therefore, ORF45-induced Filamin A phosphorylation starts from the immediately early stage of primary infection and promotes the de novo infection, likely facilitating the capsid transport to the nucleus." (PMID 41284726, 2025). "Furthermore, we found that H1N1 and porcine circovirus type 2 infection also significantly promoted the expression of FLNA and ITGα5 and increased the infection of multiple bacteria." (PMID 40937850, 2025). "In addition, it is expressed immediately after primary infection, subsequently inducing RSK activation and Filamin A phosphorylation during the immediately early stage of primary infection." (PMID 41284726, 2025). "Thus, we conclude that ORF45 and Filamin A phosphorylation play the important roles for KSHV de novo infection with cell-free viral particles." (PMID 41284726, 2025).
infection (continued). "Furthermore, a truncated version of IRE1 (ire1-Δ965) lacking the proline-rich carboxy-terminal segment of IRE1 that binds filamin A was also impaired in cell migration following infection." (PMID 32636244, 2020). "In order to determine if the abnormal filamin A phenotype could be the result of a paracrine mediated host response to infection, we exposed BPH-1 cells to culture supernatants obtained from sham inoculated or U. parvum infected cultures." (PMID 21507248, 2011). "Filamin A dynamics were perturbed in both models of infection." (PMID 21507248, 2011). "Despite these limitations, both models of infection displayed a perturbation of filamin A dynamics, which may serve as a viable molecular marker for delineating the host cell signal transduction pathways that are affected by U. parvum infection." (PMID 21507248, 2011). "Disruption of the cytoskeleton following infection with HIV has been attributed to Nef among other viral proteins, but the enriched proteins here lacked known targets of Nef but instead included Rho-associated kinase 1, an interactor of HIV Tat, and filamin-A, an interactor of HIV Gag." (PMID 35017099, 2022). "We showed that Toxoplasma alters the morphology of its host cells through IRE1-filamin A interactions, which directs cytoskeletal remodeling that contributes to a hypermigratory phenotype that facilitated dissemination of the parasite into multiple organs of the infection host." (PMID 32636244, 2020). "Further IFN and antiviral related proteins were upregulated upon infection with PeV-A3 (EIF2AK2, STAT1), or PeV-A1 (NCAM1, POM121), and downregulated upon PeV-A1 infection (EIF4G1, UBE2N, RANBP2, FLNA)." (PMID 38514653, 2024). "Three key proteins, including FLNA, TXN, and CYCS, were subjected to Western blot analysis at 0, 4, and 24 h post infection (hpi) to validate the iTRAQ process." (PMID 37264422, 2023). "Concordantly, FLNA protein levels were found to be down-regulated significantly at 12 and 24 h post-IAV PR8 and HKX31 infection." (PMID 33101257, 2020). "FLNA has been reported to regulate the actin cytoskeleton to facilitate HCV and HIV-1 infection." (PMID 37264422, 2023). "In the context of cytoskeleton dynamics, actin adaptors and enzymes that reorganize, stabilize and sever cortical F-actin, such as MSN (moesin), FLNA (filamin A), and GSN (gelsolin) have been involved in early infection, and are responsible for pore fusion and viral entry." (PMID 33995324, 2021). "Furthermore, the timing of Filamin A phosphorylation was investigated during KSHV primary infection, the level of Filamin A phosphorylation was immediately induced by both Bac16 and STOP45 viruses at 30 min post-infection probably through virion-binding cell surface receptors." (PMID 41284726, 2025). "Similarly, the primary infection of Bac16 viruses promoted the cell migration in WT cells but not in Filamin A KO or KI cells, and the primary infection of STOP45 viruses barely affected the cell migration in all cells." (PMID 41284726, 2025). "Therefore, HIV-1 uses moesin and filamin-A to promote the aggregation of HIV-1 receptors in a pole of the cell, thereby regulating CD4/CXCR4-CCR5 diffusion at the cell surface in an actin cytoskeleton-dependent manner to facilitate the first events of the infection process." (PMID 37685911, 2023).
skeletal dysplasia (12 papers, 2016 to 2024). Any Mendelian diseases that affects growth and development of the skeleton. "Alterations in the FLNA gene are associated with a wide phenotypic spectrum including brain periventricular nodular heterotopia and skeletal dysplasia." (PMID 36943452, 2023). "Herein, we report a novel FLNA mutation in a fetus with severe skeletal dysplasia in a pregnant multigravida female with a history of repeated miscarriages and terminations." (PMID 36509760, 2022). "Here, we present the crystallographically-resolved atomic structure of domains 16 and 17 of the human FLNb, and also how skeletal dysplasia associated mutations interfere in the structure and function of both FLNa and FLNb." (PMID 28652603, 2017). "Mutations in FLNA are primarily associated with skeletal dysplasias but no macroscopic features to suggest skeletal defects with mouse models such as micrognathia and other skeletal malformations." (PMID 36734119, 2023). "In addition, FLNA is a causal gene of OPDSD, and missense point mutations cause a large range of clinical symptoms in females, such as palatoschisis, palpebral fissures, micrognathia, cardiovascular abnormity, skeletal dysplasia and other organ deformities, through gain‐of‐function effects." (PMID 36734119, 2023).
genetic diseases (6 papers, 2013 to 2025). "In fact, mutations in Filamin A are responsible for a variety of genetic diseases related to cell morphological changes." (PMID 33535532, 2021). "FLNA mutations cause a wide spectrum of phenotypically overlapping genetic diseases." (PMID 32085749, 2020). "These approaches have been successful in reconstructing the phenotypes observed in patients carrying FLNA defects, indicating that impaired filamin-A is likely responsible for several human genetic diseases." (PMID 23388158, 2013).
neurological disorders (5 papers, 2014 to 2025). "Disruptions in FLNA function can impair these processes, leading to developmental and neurological disorders." (PMID 40365811, 2025). "Five known PKA substrates (FLNA, ACTB, SOX9, MAP4K1 and GBF1) interacted with the domain modules of NBEA and three of these are linked with neurological disorders (FLNA, ACTB, SOX9)." (PMID 26999814, 2016). "Dysregulation of FLNA function can impair mechanotransduction and disrupt the interaction between intracellular and extracellular signalling pathways, potentially leading to developmental abnormalities and neurological disorders." (PMID 40365811, 2025).
cardiovascular disease (3 papers, 2018 to 2023). "Mutations of the following genes can lead to cardiovascular disease: Filamin A, EMD (emerin), LAMP2 (lysosomal-associated membrane protein 2), DMD (dystrophin), TAZ (tafazzin), and VEGF-D (vascular endothelial growth factor D)." (PMID 30459711, 2018). "Notably, mutations and altered expression of IGFBP7 and FLNA have been observed in various cardiovascular diseases." (PMID 37036839, 2023). "Moreover, decrease in ADAR2 mediated editing of another actin-binding protein, filamin A (FLNA), have been linked to cardiovascular disease and reduced systolic output." (PMID 31039163, 2019).
adenocarcinoma (2 papers, 2015 to 2017). A common cancer characterized by the presence of malignant glandular cells. "The observation that increased filamin A expression predicts poorer overall survival of the never-smoked patients and adenocarcinoma provided compensatory supporting evidence suggesting involvement of filamin A in lung malignancy." (PMID 25944616, 2015). "Last, in patients without PrCa, FLNA and FLNB blood levels were positively correlated, while in patients with adenocarcinoma the relationship is dysregulated." (PMID 28344825, 2017).
respiratory diseases (2 papers, 2021 to 2023). "Undoubtedly, increasing evidence has suggested that FLNA participates in the pathogenesis of cardiovascular, cerebrovascular and respiratory diseases, in which the interaction of FLNA with transcription factors dictate the function of vascular cells." (PMID 37446373, 2023). "Recently, increasing evidence suggests that FLNA participates in the pathogenesis of cardiovascular and respiratory diseases, in which the interaction of FLNA with transcription factors and/or cell signaling molecules dictate the function of vascular cells." (PMID 34207234, 2021).
vasculopathy (2 papers, 2012 to 2024). "Moreover, the early embryonic lethality seen in null FLNA mutations in males likely arises from excessive bleeding due to a vasculopathy." (PMID 24278701, 2012). "Loss of integrity of the liningcanalsobe appreciated in blood vessels where the embryonic lethality of null FlnA mice isdue to a vasculopathy and bleeding frombreakdown of the endothelial lining." (PMID 24278701, 2012).